RPS4XP22 (ribosomal protein S4X pseudogene 22)
Synonyms: RPS4P22; RPS4X_8_1621
Gene: Processed pseudogene on chromosome 19 (9,683,294 to 9,684,073, reverse strand). Ensembl gene ENSG00000239830.
Diseases named in the same sentence as RPS4XP22 in open-access papers:
RPS4XP22 is named in the same sentence as 1 disease in open-access papers, as found by Europe PMC text mining. Sharing a sentence is not in itself a finding about the gene and the disease. The quoted sentences say what the papers report.
schizophrenia (1 paper, 2024). A major psychotic disorder characterized by abnormalities in the perception or expression of reality. "From total 66 DEGs, we identified 11 (16%) as pseudogenes, which comprised two main groups: mitochondrial pseudogenes increased in females (MTND1P23, MTCO1P12, MTCO1P40, and MTND2P28) and ribosomal pseudogenes increased in male schizophrenia patients (RPS4XP22, RPS16P4, and RPS28P7)." (PMID 39068467, 2024).